GSTP1 (glutathione S-transferase pi 1)
Diseases named in the same sentence as GSTP1 in open-access papers (continued):
Sharing a sentence is not in itself a finding about the gene and the disease.
prostate carcinoma (continued). "GSTP1 methylation has been proposed by many research papers as an epigenetic marker for early prostate cancer diagnosis and it is certainly the most widely studied epigenetic marker in prostate cancer in the last decade." (PMID 27594734, 2016). "Methylated GSTP1 in plasma was a better predictor of overall survival than PSA in prostate cancer patients." (PMID 26764421, 2016). "Alterations in epigenetic marks (i.e., hypermethylation events) are useful biomarkers; for example, MGMT epigenetic alterations are useful biomarkers in glioblastomas and GSTP1 alterations are useful in prostate cancers." (PMID 27027429, 2016). "For example, GSTP1 is methylated in >90% of prostate cancers, STRATIFIN is methylated in 96% of breast cancers and HOXA9 and EN1 are methylated in 95 and 80% of ovarian tumors respectively." (PMID 26764421, 2016). "We identified five highly methylated genes in prostate cancer: GSTP1, RARB, RASSF1, SCGB3A1, CCND2 (P < 0.0001), with an area under the ROC curve varying between 0.89 (95 % CI 0.82–0.97) and 0.95 (95 % CI 0.90–1.00)." (PMID 27576364, 2016). "We investigated GSTP1 methylation status with methylation specific PCR (MS-PCR) in prostate cancer (PCa) and in benign tissue of 56 prostatectomies." (PMID 27594734, 2016). "For this study, the 1.5 kb promoter present within the second CpG islands of the GSTP1 gene was applied, which is hypermethylated in prostate cancer cells." (PMID 27658199, 2016). "The induction of MBD‐TET1‐CDwt demethylated and upregulated glutathione S‐transferase pi 1 (GSTP1), one of the hypermethylated genes in prostate cancer." (PMID 27457352, 2016). "Accordingly, glutathione S‐transferase pi 1 (GSTP1) that is known to be one of the frequently hypermethylated genes in prostate cancer, gradually upregulated its expression from day 2 after tetracycline addition." (PMID 27457352, 2016). "The tumour-specific methylation changes at the HES5 promoter were consistent within and between cases and comparable with the hypermethylation observed at the GSTP1 gene, which is invariably silenced in prostate cancer and has been extensively studied." (PMID 25560400, 2015). "For example, GSTP1 silencing was the most frequently detected epigenetic alterations characteristic of over 90% prostate cancer samples but rarely detected in the BPH/normal tissues." (PMID 25938433, 2015). "Further, this can explain the difference between our results regarding the prognostic biomarker potential of APC and GSTP1 and a previous study where prostate cancer-specific death was also the primary endpoint." (PMID 25193387, 2014). "The gold standard for promoter hypermethylation-inactivated genes in prostate cancer (GSTP1) was repressed in 90% of our patient samples." (PMID 26317032, 2014). "In prostate cancer cells, phenethyl isothiocyanate, a phytochemical found in large amounts in cruciferous vegetables, was reported to restore expression of silenced GSTP1 by a mechanism involving promoter demethylation and increased histone acetylation." (PMID 25076909, 2014). "Hypermethylation of GSTP1, one of the first epigenetic biomarkers to be implemented in the clinic, is used for early diagnosis of prostate cancer." (PMID 25473433, 2014). "In prostate cancer, numerous hypermethylated genes have been found, with GSTP1, APC1 and RARB amongst the most frequently reported, and hitherto mainly assessed for diagnostic purposes." (PMID 25193387, 2014). "Some of the commonly reported hypermethylated genes in prostate cancer include GSTP1, RASSF1A, and APC, which have aided in prostate cancer diagnosis and prognosis." (PMID 24664224, 2014). "The CpG sites in GSTP1 were 99.00% methylated in LNCaP and 78.46% methylated in PC-3 cell lines, indicating that the sequenced region in the two prostate cancer cell lines was hypermethylated at baseline." (PMID 25389438, 2014).
prostate carcinoma (continued). "One study showed that the frequency of GSTP1 Val/Val genotype was 14.3% in prostate cancer cases compared with 2.4% in controls, providing a notion that there is a significant association (OR: 3.72, 95% CI: 1.67–5.65; P = 0.002)." (PMID 23977100, 2013). "Although GSTP1 methylation is a well known event in the carcinogenesis of prostate cancer, its role in bladder carcinoma has yet to be defined." (PMID 24252461, 2013). "As in previous studies of PhIP-induced prostatic neoplasia in rodents, we found that the GSTP1 protein, which is silenced via promoter methylation in ∼90% of human prostate cancers, was decreased in cribiform PIN/CIS lesions in the rat ventral prostate." (PMID 24312188, 2013). "We found a strong association between presence of APC and GSTP1 methylation in NTAT and long-term mortality and 5-year mortality from prostate cancer." (PMID 23874531, 2013). "Methylation of GSTP1 (glutathione S-transferase) promoter is the most extensively investigated epigenetic change in prostate cancer." (PMID 23874531, 2013). "GSTP1 DNA methylation and protein expression status is correlated with 5-aza-2′-deoxycytidine treatment response in prostate cancer cells." (PMID 22792345, 2012). "Pi-class glutathione S-transferases (GSTP1) protect the cell from cytotoxic and carcinogenic agents and have been found to be hypermethylated and silenced in prostate cancer tissue." (PMID 22284215, 2012). "Based on the findings of this study, we propose that GSTP1 is a marker of DNMTi treatment efficacy in prostate cancer." (PMID 21980513, 2011). "The purpose of this study was to conduct a meta-analysis on the sensitivity and specificity of GSTP1 methylation in body fluids on prostate cancer detection." (PMID 21654682, 2011). "If GSTP1 promoter hypermethylation can be detected in body fluids and if it accurately predicts prostate cancer, then this measurement has the potential to complement PSA screening." (PMID 21654682, 2011). "We performed a methyl-CpG pull-down with U937 nuclear extracts in forward and reverse using oligos containing part of the sequence of the human GSTP1 CpG-island; its hypermethylation is characteristic in prostate cancer." (PMID 21991380, 2011). "Its relevance to the genesis of prostate cancer is illustrated by methylation of the glutathione S-transferase (GSTP1) gene." (PMID 21867542, 2011). "One of the earliest changes in the pathogenesis of prostate cancer is CpG island hypermethylation at the glutathione S-transferase (GSTP1) gene." (PMID 22191037, 2011). "Studies have shown that glutathione-s-transferase—π (GSTP1) promoter hypermethylation is the most common somatic genome alteration during prostate cancer development." (PMID 21654682, 2011). "GSTP1 methylation appears to discriminate between benign and premalignant/malignant prostate and persists through all stages of prostate cancer, and can be detected in circulating tumor cells (CTCs)." (PMID 22191037, 2011). "We have shown that GSTP1 DNA methylation and protein expression status is correlated with DNMTi treatment response in prostate cancer cells." (PMID 21980513, 2011). "GSTP1 is hypermethylated in nearly all human prostate cancers and its promoter DNA methylation level is able to differentiate between benign prostatic hyperplasia and different grades of prostate adenocarcinoma." (PMID 21980513, 2011). "To investigate the efficacy of 5-aza-CdR and Zebularine in prostate cancer cells, we examined DNA methylation and expression status of the glutathione-S-transferase P1 (GSTP1) gene." (PMID 21980513, 2011). "Since GSTP1 is methylated in nearly all prostate cancers, our results warrant its testing as a marker of epigenetic therapy response in future clinical trials." (PMID 21980513, 2011). "We found that GSTP1 promoter methylation increased with prostate cancer pathological stage (stages 3–4 vs 1–2), with an odds ratio of 1.66 (95% CI, 0.86–3.19)." (PMID 21654682, 2011).
prostate carcinoma (continued). "The repressed expression of antioxidant and detoxifying enzymes such as GSTP1 in prostate cancer has extensively been studied." (PMID 20062804, 2010). "A straightforward interpretation of this finding is that EPB41L3 hypermethylation occurs in many prostate cancers in conjunction with or following the hypermethylation of GSTP1." (PMID 20860828, 2010). "Hypermethylation of GSTP1 was found in 94% of tumors, 72% of plasma or serum samples, 50% of ejaculate, and 36% of urine from patients with prostate cancer." (PMID 20671914, 2010). "Of all the genes known to be methylated in prostate cancer, GSTP1 is the most frequently methylated gene." (PMID 20671914, 2010). "A racial difference in the methylation status of the GSTP1, CD44, ESR, and CDH1 genes is associated with prostate cancer." (PMID 20671914, 2010). "A combination of four genes (p16, ARF, MGMT, and GSTP1) has been proposed to detect prostate cancer with an estimated 87% sensitivity and 100% specificity." (PMID 19662228, 2008). "One candidate, IGFBP3, was selected for investigation, along with glutathione-S-transferase pi (GSTP1), a well-known methylation target in prostate cancer." (PMID 17453001, 2007). "The high prevalence of GSTP1 hypermethylation in prostate cancer, HGPIN and in some proliferative inflammatory atrophy lesions indicates that it most likely precedes many other molecular aberrations in prostate carcinogenesis." (PMID 17453001, 2007). "Although GSTP1 is widely recognised as an excellent biomarker of prostate cancer, used alone it has limitations." (PMID 17453001, 2007). "Another cancer related gene is GSTP1, which was reported to be lost in different types of cancers including prostate cancer, lung cancer and squamous cell carcinoma." (PMID 19458770, 2007). "The purpose of our study was to assess the impact of endocrine therapy on the detection of GSTP1-HM by methylation-specific PCR (MSP) in prostate cancer." (PMID 16803634, 2006). "Glutathione S-Transferase P1 (GSTP1) and Retinoic Acid Receptor 2 (RARβ2) were selected as markers given that their methylation has been previously shown to be more prevalent in prostate cancer cells." (PMID 16512911, 2006). "GSTP1-CpG island hypermethylation (GSTP1-HM) has been shown to be a promising new marker of prostate cancer, which is supposed to be able to overcome some of the disadvantages of PSA." (PMID 16803634, 2006). "The GSTP1 gene is frequently hypermethylated in prostate cancers, but is a less than ideal candidate for a tumour suppressor." (PMID 15292941, 2004). "Additionally, GSTP1, one of the most frequently hypermethylated genes in prostate cancer and a proposed caretaker gene, displayed pronounced hypermethylation of a TMR located just downstream of its TSS." (PMID 41036619, 2025). "We believe that GSTP1 is able to reduce the risk of prostate cancer, which is expected to be a potential therapeutic target for prostate cancer, and also allows us to recognize the non-negligible role of GSH metabolism for prostate cancer." (PMID 40426879, 2025). "DNA methylation, the most common epigenetic modification, plays a role in tumor cells; promoter hypermethylation of the GSTP1 gene is detected in prostate cancer, and this alteration is strictly limited to malignant cells, including prostate cancer and prostatic intraepithelial neoplasia." (PMID 40426879, 2025). "Similarly, GSTP1 was overexpressed in colon cancer but downregulated in prostate cancer, while PDGFRB showed an overexpression in liver cancer and downregulation in lung cancer." (PMID 39594421, 2024). "Methylation of GSTP1 is frequently observed in prostate cancer tissue but is rare in normal prostate tissue, which suggests that methylated GSTP1 in cfDNA may serve as a biomarker for prostate cancer diagnosis." (PMID 36747996, 2023).
prostate carcinoma (continued). "Studies have investigated whether certain genetic alterations in Glutathione S-transferases (GSTs)—GSTP1, GSTM1, and GSTT1—that play a role in carcinogen metabolism and defense against reactive oxygen species are linked to prostate cancer risk." (PMID 37175108, 2023). "Among the prostate cancer patients, the minimum proportion of GSTP1 genes methylated in any of the 17 positions was 12.1% of the total circulated DNA fragments, and the minimum proportion of GSTP1 genes methylated in any of the 11 diagnostically specific positions was 8.4%." (PMID 36672380, 2023). "The results of the meta-analysis substantiate the high specificity of promoter methylation of GSTP1 in cfDNA for the diagnosis of prostate cancer, and it may be used to more precisely evaluate the prognosis of patients with prostate cancer." (PMID 36747996, 2023). "This interaction suggests that drugs designed to target GSTP1 might inhibit androgen synthesis or boost the efficacy of other drugs, such as 5-fluorouracil, in inhibiting DNA synthesis for the treatment of prostate cancer." (PMID 37735436, 2023). "In prostate cancer, epigenetic silencing of the glutathione-S-transferase P1 (GSTP1) gene may be important in the development of tumors (Henrique and Jerónimo 2004)." (PMID 36892747, 2023). "Therefore, we performed a meta-analysis of published clinical studies to assess the relationship between GSTP1 promoter methylation in cfDNA and the diagnosis and prognosis of prostate cancer." (PMID 36747996, 2023). "In conclusion, our meta-analysis demonstrated that GSTP1 promoter methylation in cfDNA may be used as a potential biomarker for prostate cancer and has high clinical value for the diagnosis and prognosis of PCa." (PMID 36747996, 2023). "Importantly, many of these genes are methylated in more than 75% of patients, with some genes like GSTP1 being methylated in over 95% of patients with prostate cancer." (PMID 35272673, 2022). "Recently, attention has focused on prostate cancer cases in which GSTP1 expression is retained." (PMID 35104804, 2022). "For example, GSTP1 affects the toxicity efficiency of docetaxel and paclitaxel in breast cancer cells, platinum drugs in ovarian cancer cells, and ionizing radiation in prostate carcinoma cells." (PMID 34209254, 2021). "Others also reported that the combination of non-functionnal GSTP polymorphisms or the presence of GSTP1 methylation in prostate tissue were predisposing factors for prostate cancer." (PMID 34154586, 2021). "Additional studies are underway to determine whether GSTP1 positive cases differ in terms of rates of biochemical recurrence, metastatic disease and deaths due to prostate cancer." (PMID 34191807, 2021). "Given the large breadth of molecular alterations in prostate cancer, additional studies with larger numbers of patients are required to determine whether GSTP1 positive cases represent a distinct molecular subtype of prostate cancer." (PMID 34191807, 2021). "Our goal was to begin to determine whether GSTP1-positive prostate cancer represents a distinct molecular subtype, and, whether the prevalence of GSTP1-positivity differs between Black and White men." (PMID 34191807, 2021). "The latest reports on this polymorphism, cited in the meta-analysis of Wei and co-workers 2013, indicate a lack of dependence between GSTP1 Ile/Ile, Ile/Val, and Val/Val variants and an increased risk of prostate cancer." (PMID 32212077, 2020). "Hypermethylation of APC, RASSF1, PTG2, and MDR1 has also been observed in prostate cancer samples, and the combination of these markers with GSTP1 has been demonstrated to be capable of reliably distinguishing between primary cancer and benign tissue with high sensitivity and specificity." (PMID 31097014, 2019). "Gstp1 methylation status in urine is strongly correlated with early onset of prostate cancer." (PMID 31608277, 2019).
prostate carcinoma (continued). "The finding of an association between GSTP1 hypermethylation in non-tumor prostate tissue from a negative biopsy and the risk of prostate cancer detection in a later biopsy was replicated in both wards included in our study." (PMID 31666119, 2019). "Moreover, promoter methylation of GSTP1 gene was detected in some body fluids of patients with prostate cancer and was proposed as a biomarker candidate for noninvasive detection of prostate cancer." (PMID 30043549, 2018). "Within hypermethylated c-HMRs, we detected previously reported frequent DNA hypermethylation at gene promoters such as MGMT in glioblastoma, NSD1 in neuroblastoma, ESR1 in breast cancer, GSTP1 in prostate cancer and the promoter hypermethylation of RASSF1 in various cancer contexts." (PMID 28581523, 2017). "In addition to many novel candidates, this list contained several genes known to be frequently hypermethylated in prostate cancer (e.g. GSTP1, RARB), supporting the validity of our results." (PMID 28052017, 2017). "For example, the presence of methylated GSTP1 DNA in plasma has been used to track the response of prostate cancer patients, and methylation of a panel of ten genes varied between breast cancer patients achieving partial or complete response and those achieving no response to therapy." (PMID 28685150, 2017). "GSTP1 may be the prime candidate as studies evaluating its use as a biomarker for prostate cancer are well advanced." (PMID 28893223, 2017). "The panel of four genes (p16, ARF, MGMT, and GSTP1) could discriminate prostate cancer with a sensitivity and specificity of 87% and 100%, respectively." (PMID 28358330, 2017). "In case of one of the best characterized biomarkers, GSTP1, a meta study (mainly using prostatectomy tissue or prostate sextant biopsies) showed that hypermethylation of the promoter allows to diagnose prostate cancer with a sensitivity of 82% and a specificity of 95%." (PMID 27895806, 2016). "In addition to significant links with prostate cancer, breast cancer, ovarian cancer, and bladder cancer, GSTP1 has been found to be involved in the progression of NPC." (PMID 27149165, 2016). "Similarly, glutathione S-transferase 1 (GSTP1) promoter methylation in peripheral DNA is regarded as a potential prognostic marker of prostate cancer." (PMID 27999265, 2016). "GSTP1 is an established biomarker for prostate cancer diagnosis and prognosis." (PMID 27027429, 2016). "Low GEN concentrations applied for 1–2 weeks were sufficient to reduce DNA methylation at the promoter of GSTP1, a Phase-II metabolizing enzyme commonly silenced in prostate cancer, with subsequent weak mRNA re-expression in ER-negative MDA-MB-468 but not in ER-positive MCF-7 cells." (PMID 25322458, 2014). "Considering that the discrimination power of serum prostate-specific antigen (PSA) measurement between benign and malignant tumor cells is currently under controversial discussion, the best and the most promising epigenetic marker for prostate cancer detection is the hypermethylation of GSTP1." (PMID 25076909, 2014). "Interestingly, GSTP1 hypermethylation is strictly restricted to malignant cells including prostate cancer cells (PCa) as well as prostatic intraepithelial neoplasia (PIN)." (PMID 25076909, 2014). "By re-expressing GSTP1, increased detoxification, and reduced levels of oxidative stress could potentially contribute to reduced prostate cancer progression and even to an abrogation on evolution toward invasive and metastatic disease." (PMID 25076909, 2014). "Furthermore, it was established that GSTP1 gene was demethylated and reactivated following exposure to green tea polyphenols in prostate cancer cells." (PMID 25076909, 2014).